ADGRF2P (adhesion G protein-coupled receptor F2, pseudogene)
Description:
Orphan receptor.
Synonyms: PGR20; hGPCR35; formerly GPR111; ADGRF2
Target class: Family B G protein-coupled receptor; Membrane receptor
Gene: Transcribed unitary pseudogene on chromosome 6 (47,673,420 to 47,693,719, forward strand). Ensembl gene ENSG00000164393.
Subcellular location: Membrane
Diseases named in the same sentence as ADGRF2P in open-access papers:
ADGRF2P is named in the same sentence as 5 diseases in open-access papers, as found by Europe PMC text mining. Sharing a sentence is not in itself a finding about the gene and the disease.
ADGRF2P shares sentences with these, for which no sentence is quoted: infection (2 papers); atherosclerosis (1); cancer (1); glioma (1); tumor (1).